C1QTNF7 (C1q and TNF related 7)
Synonyms: CTRP7; ZACRP7
Tractability: Antibody: UniProt places it where antibodies can reach, with high confidence; UniProt predicts a signal peptide or a membrane-spanning region; its Gene Ontology location is reachable by antibodies, with medium confidence.
Gene: Protein-coding gene on chromosome 4 (15,339,818 to 15,446,167, forward strand). Ensembl gene ENSG00000163145.
Subcellular location: Secreted
Subcellular location (Human Protein Atlas): Vesicles; Predicted to be secreted
Gene Ontology:
Cellular component: extracellular region
Genetic constraint (gnomAD): Loss-of-function variants: 15 observed, 20.63 expected, observed/expected ratio (o/e) 0.73, 90% interval 0.49 to 1.12. The upper end of that interval is the gene's LOEUF score, 1.12, which puts it in group 4 of 6, group 1 being the genes least tolerant of losing a copy. Missense variants: 324 observed, 379.42 expected, observed/expected ratio (o/e) 0.85, 90% interval 0.78 to 0.94. Synonymous variants: 142 observed, 144.8 expected, observed/expected ratio (o/e) 0.98, 90% interval 0.86 to 1.13.
Homologues: Orthologues: chimpanzee C1QTNF7 (100% identical), macaque C1QTNF7 (99% identical), pig C1QTNF7 (97% identical), rat C1qtnf7 (97% identical), dog C1QTNF7 (97% identical), mouse C1qtnf7 (97% identical), guinea pig C1QTNF7 (96% identical), rabbit C1QTNF7 (96% identical), tropical clawed frog cc2d2a (78% identical), zebrafish c1qtnf7 (66% identical). Paralogues in human: C1QTNF2 (56% identical), C1QTNF9 (40% identical), C1QTNF9B (40% identical), COL10A1 (38% identical), COL8A2 (36% identical), OTOL1 (35% identical), ADIPOQ (34% identical), COL8A1 (33% identical), C1QTNF5 (33% identical), C1QC (30% identical), C1QB (29% identical), C1QL2 (28% identical), and 11 more.
Diseases named in the same sentence as C1QTNF7 in open-access papers:
C1QTNF7 is named in the same sentence as 22 diseases in open-access papers, as found by Europe PMC text mining. Sharing a sentence is not in itself a finding about the gene and the disease. The quoted sentences say what the papers report.
Obesity (4 papers, 2017 to 2022). Accumulation of substantial excess body fat. "The C1QTNF7 transcripts were found to be expressed predominantly in the adipose tissue, and deletion of C1QTNF7 attenuated obesity-linked glucose intolerance, adipose tissue inflammation, and hepatic stress." (PMID 29739312, 2018). "It is noteworthy that multiple C1q homologs, adiponectin, FCN1–2, and C1qTNF7 showed changes in obesity." (PMID 28559893, 2017).
virus infection (1 paper, 2020). "C1QTNF7 is also part of the interaction network of the BCL-2 athanogene 3 (BAG3), which plays multiple roles in physiological and pathologic processes, including antiapoptotic activity, signal transduction, virus infection, cell adhesion and migration, and initiation of autophagy." (PMID 32650713, 2020).
C1QTNF7 also shares sentences with these, for which no sentence is quoted: Glucose intolerance (2 papers); Hyperglycemia (2); infection (2); metabolic disease (2); metabolic syndrome (2); Abdominal obesity (1); angiosarcoma (1); cancer (1); coronary artery disease (1); diabetes (1); glucose-metabolism disorder (1); head and neck tumours (1); hepatoma (1); Hyperinsulinemia (1); Impaired glucose tolerance (1); Insulin resistance (1); liver fibrosis (1); lung carcinoma (1); prediabetes (1); type 2 diabetes mellitus (1).